ZCCHC17 (zinc finger CCHC-type containing 17)
Synonyms: pNO40; PS1D; HSPC251
Tractability: PROTAC: ubiquitination databases record sites on it.
Gene: Protein-coding gene on chromosome 1 (31,296,982 to 31,365,527, forward strand). Ensembl gene ENSG00000121766.
Subcellular location: Nucleus, nucleolus
Gene Ontology:
Molecular function: identical protein binding; protein binding; RNA binding; nucleic acid binding; zinc ion binding
Cellular component: cytosolic large ribosomal subunit; nucleolus
Genetic constraint (gnomAD): Loss-of-function variants: 16 observed, 28.6 expected, observed/expected ratio (o/e) 0.56, 90% interval 0.38 to 0.85. The upper end of that interval is the gene's LOEUF score, 0.85, which puts it in group 3 of 6, group 1 being the genes least tolerant of losing a copy. Missense variants: 253 observed, 284.15 expected, observed/expected ratio (o/e) 0.89, 90% interval 0.8 to 0.99. Synonymous variants: 83 observed, 93.81 expected, observed/expected ratio (o/e) 0.88, 90% interval 0.74 to 1.06.
Homologues: Orthologues: guinea pig Zcchc17 (98% identical), mouse Zcchc17 (95% identical), rat Zcchc17 (95% identical), chimpanzee ZCCHC17 (93% identical), rabbit ZCCHC17 (90% identical), macaque ZCCHC17 (85% identical), pig ZCCHC17 (77% identical), tropical clawed frog zcchc17 (64% identical), dog ZCCHC17 (60% identical), zebrafish zcchc17 (58% identical).
Diseases named in the same sentence as ZCCHC17 in open-access papers:
ZCCHC17 is named in the same sentence as 6 diseases in open-access papers, as found by Europe PMC text mining. Sharing a sentence is not in itself a finding about the gene and the disease. The quoted sentences say what the papers report.
Alzheimer disease (3 papers, 2021 to 2026). A progressive, neurodegenerative disease characterized by loss of function and death of nerve cells in several areas of the brain leading to loss of cognitive function such as memory and language. "ZCCHC17 has recently been proposed as a master regulator in Alzheimer’s disease and is expressed in neuronal cells where levels are seen to drastically decrease early in AD, before significant neuronal cell loss or gliosis." (PMID 35093178, 2022). "RBP ZCCHC17, which has unique negative correlation with NAPRT expression, has been scarcely studied, but the most relevant studies place it as a regulator in Alzheimer’s disease." (PMID 34946971, 2021).
glioma (1 paper, 2024). A benign or malignant brain and spinal cord tumor that arises from glial cells (astrocytes, oligodendrocytes, ependymal cells). "No data on the involvement of such genesas ASCC1, ZCCHC17 (participates in biogenesisof ribosomal DNA), PLAT, CISD1,TMEM229a and RANBP3L in the development and spread ofany glioma types have been found." (PMID 39539523, 2024).
tumor (2 papers, 2021 to 2023). "For this reason, this study is the first to analyze the role of ZCCHC17 as a tumor diagnostic marker." (PMID 35071004, 2021). "Further multivariate Cox regression analysis showed that Stage III and Stage IV, With tumor, The expression level of ZCCHC17 is an independent risk factor affecting the prognosis of HCC patients." (PMID 35071004, 2021). "Univariate Cox regression analysis showed that Stage III and Stage IV, With tumor, and the expression level of ZCCHC17 was a risk factor for the prognosis of HCC patients." (PMID 35071004, 2021). "The results showed that the ZCCHC17 expression in the tumor was higher than normal, and the difference between the two groups was 0.935 (0.755-1.114)." (PMID 35071004, 2021). "The results showed that the expression level of ZCCHC17 in the tumor was significantly higher than that in normal (P<0.001)." (PMID 35071004, 2021). "At the same time, we downloaded the expression profile data of HCC patients from GSE54236, GSE84005, and ICGC to validate the expression difference of ZCCHC17 between tumor and non-tumor samples." (PMID 35071004, 2021). "The analysis of TCGA unpaired samples showed that the expression level of ZCCHC17 in the tumor was significantly higher than that of normal, and the difference was statistically significant (P <0.001)." (PMID 35071004, 2021). "The comparison results still show that the expression level of ZCCHC17 in the tumor is significantly higher than that of normal (P <0.001)." (PMID 35071004, 2021). "Therefore, we did a methylation analysis to explore further the reasons for the abnormally high expression of ZCCHC17 in tumor samples." (PMID 35071004, 2021). "By downloading the methylation data of HCC patients from TCGA and analyzing the correlation between the methylation level of different CpG sites and the expression level of ZCCHC17, we found that the methylation level of ZCCHC17 in normal tissues was significantly higher than that in tumor tissues." (PMID 35071004, 2021). "Our research has shown that ZCCHC17 is highly correlated with immune cells in TME, indicating that ZCCHC17 may help tumor cells to immune escape by affecting the Th1/Th2 balance, thereby promoting the occurrence of HCC." (PMID 35071004, 2021). "The abnormally high expression may be related to the abnormal DNA methylation of ZCCHC17 in tumor tissues." (PMID 35071004, 2021). "The high expression of ZCCHC17 is related to AFP, histologic grade, tumor status, vascular invasion, and pathological stage." (PMID 35071004, 2021). "The results showed significant differences in the expression of ZCCHC17 in different subgroups of AFP, histologic grade, tumor status, vascular invasion and pathological stage." (PMID 35071004, 2021). "We found that ZCCHC17 has strong specificity and can effectively distinguish tumor and non-tumor samples." (PMID 35071004, 2021). "All in all, these results confirm that ZCCHC17 is used as an HCC diagnosis and as an independent prognostic biomarker and may promote the development of tumor-targeted therapy and tumor immunotherapy." (PMID 35071004, 2021).
ZCCHC17 also shares sentences with these, for which no sentence is quoted: cancer (1 paper); Fanconi anemia complementation group M (1); hepatocellular carcinoma (1).